CLDN1 (claudin 1)
Diseases named in the same sentence as CLDN1 in open-access papers (continued):
Sharing a sentence is not in itself a finding about the gene and the disease.
atopic dermatitis (41 papers, 2016 to 2026). "While Cldn1−/− mice die within the first day of life due to transepidermal water loss, the Claudin 1 knockdown showed a disintegration of the epidermis that resembled atopic dermatitis." (PMID 41481333, 2026). "Downregulation of Cldn1 has also been reported in diseases associated with dry skin, such as atopic dermatitis and psoriasis." (PMID 40940777, 2025). "In fact, CLDN1-deficient mice are reported to die within 1 day of birth, and clinical studies have demonstrated CLDN1 suppression in the case of atopic dermatitis and NISCH syndrome." (PMID 38332234, 2024). "Decreased levels of the transmembrane protein claudin-1 (CLDN1), a major component of TJs, are strongly associated with atopic dermatitis, leading to barrier function impairment and increased inflammation." (PMID 39202657, 2024). "Polymorphisms in the CLDN1 gene encoding claudin-1, tight junction transmembrane protein, was associated with atopic dermatitis and increased TEWL." (PMID 36904070, 2023). "At the mRNA level, calcitriol enhanced the expression of claudin-1, occludin, and tight junction protein 1 (Tjp1, gene encoding ZO-1) in NC/Nga mice with atopic dermatitis." (PMID 37298299, 2023). "Accordingly, the down-regulation of Cldn-1 has been associated with impaired skin barrier function, enhanced skin permeability, and skin pathologies, such as psoriasis and atopic dermatitis." (PMID 34884896, 2021). "A decrease in CLDN1 expression in atopic dermatitis is related to increased susceptibility to herpes simplex virus-1 infection, the expression of Th2 immune markers, and the number of serum IgEs and eosinophils." (PMID 32326002, 2020). "Claudin-1 downregulation has been linked to atopic dermatitis (AD) pathogenesis but variable levels of claudin-1 have also been observed in healthy skin." (PMID 32029783, 2020). "This indicates that CLDN1 is also associated with the immune abnormalities of patients with atopic dermatitis and their susceptibility to infection." (PMID 32326002, 2020). "Moreover, the downregulation of claudin-1 has been associated with the inflammatory process in atopic dermatitis and various tumours." (PMID 39201334, 2024). "Moreover, claudin-1 knockdown in mice caused epithelial barrier dysfunction and morphological features of atopic dermatitis in the skin, including hyperkeratosis, acanthosis, and neutrophil infiltration." (PMID 36496820, 2022). "Furthermore, decreased claudin-1 expression in tight junctions is found to be associated with reduced immune response and skin diseases such as atopic dermatitis and psoriasis." (PMID 29273721, 2017). "However, expression changes of claudin 1 may be a critical risk factor for the pathogenesis and progression of skin diseases such as atopic dermatitis." (PMID 36647127, 2023). "MiR-155-5p can indirectly reduce the expression of Cldn1 and occludin by binding to protein kinase inhibitor α, thereby increasing skin barrier permeability and contributing to the onset of atopic dermatitis." (PMID 40940777, 2025). "In patients with atopic dermatitis, a decrease in claudin-1 expression leads to TJ and epidermal barrier dysfunction, which results in inflammatory changes within the human epidermis." (PMID 39199247, 2024). "The results showed a decrease in tracer stops in atopic dermatitis skin compared to healthy skin correlating with claudin-1 fluorescence intensity." (PMID 39582772, 2024). "For example, claudin-1 decreased expression in atopic dermatitis correlates with a dose-dependent increase in permeability to Biotin-556 tracer." (PMID 39582772, 2024). "Pathological examinations, particularly in atopic dermatitis, reveal a reduced expression of claudin-1 (CLDN1), leading to a compromised barrier function." (PMID 39199247, 2024).
atopic dermatitis (continued). "Nectin-1 was present throughout all epidermal layers of atopic dermatitis skin; however, its distribution toward the TJ markers ZO-1 and claudin-1 strongly changed suggesting that impaired TJs make nectin-1 more accessible to the virus." (PMID 37289055, 2023). "We observed a decreased expression of claudin-1, occludin, and ZO-1 in the epidermis of NC/Nga mice with atopic dermatitis compared with control mice." (PMID 37298299, 2023). "This has been primarily correlated with the impaired barrier properties of atopic dermatitis lesions with the reduced production of Claudin-1." (PMID 37514111, 2023). "Immunohistochemical analysis showed that filaggrin, involucrin, loricrin, claudin-1, occludin, and ZO-1 were decreased in NC/Nga mice with atopic dermatitis, which is consistent with previous reports." (PMID 37298299, 2023). "The topical application of calcitriol to atopic dermatitis mice enhanced claudin-1 expression and prevented biotin diffusion into the upper layers of the epidermis." (PMID 37298299, 2023). "In patients with atopic dermatitis, it has been reported that the mRNA expression of filaggrin, loricrin, occludin, and claudin-1 was decreased, while the expression of involucrin and TJP1 was not affected compared with control subjects." (PMID 37298299, 2023). "The expression of claudin-1 was decreased in the Dfb-induced atopic dermatitis model in NC/Nga mice, and sulfo-NHS-LC-biotin diffused into the epidermis of these mice, indicating the dysfunction of tight junction barriers." (PMID 37298299, 2023). "Comparable to atopic dermatitis skin, claudin-1 was redistributed upon cytokine treatment and occludin and ZO-1 patterns were also changed." (PMID 37289055, 2023). "Knockdown of claudin-1 expression level in mouse models of atopic dermatitis and allergic asthma exacerbated allergic inflammation, proving that downregulation of claudin-1 expression level contributes to the pathogenesis of allergic diseases." (PMID 35844593, 2022). "The level of CLDN1 is significantly lower in individuals with atopic dermatitis than in healthy adults." (PMID 34683350, 2021). "CLDN1 is the most abundant claudin in humans and is thought to be a key gene in human skin disease, especially atopic dermatitis." (PMID 34683350, 2021). "PKI α can promote claudin-1 and occludin expressions, while miR-155-5p can increase skin barrier permeability and induce atopic dermatitis by indirectly down-regulating claudin-1 and occluding." (PMID 33767583, 2021). "Reduced CLDN1 levels appears to be a common theme in different chronic inflammatory skin diseases, including psoriasis, atopic dermatitis and rosacea." (PMID 32733073, 2020). "In the case of glucose, topical glucose was shown to induce claudin-1 and filaggrin expression in a mouse model of atopic dermatitis and in keratinocyte culture, indicating that it has an anti-inflammatory effect by repairing skin barrier function." (PMID 32138354, 2020). "For example, the skin of patients with atopic dermatitis exhibits reduced expression levels of ZO-1 and claudin-1, and knockdown of claudin-1 in mice induces a psoriasis-like condition." (PMID 31013709, 2019). "Knock-down of the TJ protein claudin-1, which we demonstrate here to be less expressed in HFs of lesional atopic dermatitis skin, results in impaired barrier function, decreased proliferation and increased apoptosis of hair keratinocytes." (PMID 30143655, 2018). "Another study in a mouse model of atopic dermatitis showed that the changes in skin epithelial barrier function correlated with a decreased expression of claudin-1, as indicated by changes in TEER, paracellular flux, and the morphology of the stratum corneum." (PMID 30518037, 2018). "Claudin 1, a tight junction protein, is an essential protein in epidermal barrier integrity; decreases in claudin represent a disruption of the epidermal barrier, as seen in atopic dermatitis." (PMID 38817611, 2024).
atopic dermatitis (continued). "Interestingly, calcitriol application upregulated filaggrin, loricrin, claudin-1, and Tjp1 in NC/Nga mice with atopic dermatitis." (PMID 37298299, 2023). "Tight junction dysfunction contributes to barrier failure and immunological dysregulation in Atopic Dermatitis patients, and this may be mediated in part by claudin-1 decreases." (PMID 36660532, 2023). "Costainings with claudin-1 further demonstrated nectin-1 throughout the granular layer with a punctate and reduced pattern of claudin-1 indicative of the strongly redistributed TJ marker in atopic dermatitis epidermis." (PMID 37289055, 2023). "Importantly, in patients with atopic dermatitis, asthma, and food allergy, claudin-1 expression level was significantly downregulated in the skin, bronchial and intestinal epithelium, respectively." (PMID 35844593, 2022). "Additionally, SC barrier formation is impaired in atopic dermatitis (AD) skin—a fact that coincides with the reported alteration of Cldn-1 expression and TJ defects in this disease." (PMID 35806491, 2022). "In contrast to the increase in claudin-1 expression after C. concisus infection in colonic epithelium, a recent study reported claudin-1 downregulation with a concomitant barrier dysfunction and an increase in inflammation in atopic dermatitis." (PMID 33669494, 2021). "Since these reports indicate that the expression level of CLDN1 decreased in the skin with atopic dermatitis and CLDN1 knockout mice showed skin barrier dysfunction, CLDN1 is considered as a main component for the TJ barriers in the skin among over 20 subtypes of CLDNs." (PMID 34638666, 2021). "CLDN1 expression is also markedly decreased in the epidermis of atopic dermatitis patients." (PMID 32340108, 2020). "The protein level of CLDN1 is decreased in atopic dermatitis, whereas that of CLDN4 is increased." (PMID 31398894, 2019). "In addition, a positive correlation between Cldn-1 expression and amount of proliferative cells in the epidermis was observed in an AD-like allergic dermatitis mouse model." (PMID 30143655, 2018). "However, other studies reported that increasing CLDN1 expression might improve barrier function and decrease inflammation in atopic dermatitis." (PMID 41321497, 2025). "In a similar study performed on skin samples from healthy subjects and atopic dermatitis patients, a biotin-556 tracer was injected into skin biopsies and the paracellular permeability was measured by counting the regions where the tracer colocalized with claudin-1 fluorescence (“tracer stops”)." (PMID 39582772, 2024). "Strikingly, the phenotype of mice deficient for Ctse, the expression of which was found absent in the Claudin 1–deficient DC1 lineage, is also demonstrated by atopic dermatitis." (PMID 41481333, 2026). "At the mRNA level, involucrin and occludin were downregulated, while the expression of filaggrin, loricrin, claudin-1, and Tjp1 was not changed in NC/Nga mice with atopic dermatitis." (PMID 37298299, 2023). "The claudin-1 expression has been observed to be reduced in atopic dermatitis patients' non-lesional skin." (PMID 36660532, 2023). "Reduced CLDN1 expression in the nonlesional areas of patients with atopic dermatitis and the consequent TJ abnormalities have been reported." (PMID 32326002, 2020). "In an atopic dermatitis mouse model, the absence of claudin-1 in the lower epidermal layers correlates with significantly increased proliferation of epithelial cells, as well as changes in the expression of differentiation markers keratin-10 and keratin-14." (PMID 30518037, 2018). "Indeed, emerging evidence suggests that clinically unaffected skin barrier properties in atopic dermatitis are compromised, as decreased levels of claudins-1, -4, and -23 have been found in nonlesional skin, and an inverse relationship between claudin-1 and Th2-polarized responses has been observed." (PMID 29976563, 2018).
lung carcinoma (36 papers, 2012 to 2025). "Studies have found that down-regulation of claudin-1 expression is induced by TNF-α is regulated by the PKCδ–iPLA2–PGE2–PPARγ signaling cascade in human lung carcinoma A549 cells, which caused the change of morphology and migration ability." (PMID 29311822, 2017). "This aligns with reports that high claudin expression can confer drug resistance; for instance, claudin-7 and claudin-1/2 upregulation promotes Cisplatin resistance in pancreatic and lung cancer cells." (PMID 40508219, 2025). "Among these genes, six were already identified in the lung cancer related network of genes associated with RETC634Y signature (TMEM45B, CLDN1, TRIM29, SMUG1, SATB2, and EFNA3)." (PMID 38132167, 2023). "The expression of ZO-1, Occludin and Claudin-1 protein in lung cancer mice were detected, and the repair effect on the intestinal mucosal physical barrier in lung cancer mice was investigated." (PMID 36992837, 2023). "Claudin-3 and − 4 have been implicated in cisplatin resistance induction in ovarian cancer, and claudin-1 in chemotherapy resistance in lung cancer." (PMID 37041570, 2023). "In lung cancer, CLDN1 was also shown to be involved in the development of chemoresistance to anticancer agents, including cisplatin, doxorubicin, SN-38 and gemcitabine." (PMID 37041570, 2023). "In 2007, our research group was the first to demonstrate that CLDN1, -2, -3, -4, and -7 proteins are expressed in normal bronchial epithelial cells as well as in different histologic subtypes of lung cancer." (PMID 37621953, 2023). "Conversely, it was shown that CLDN1 expression increased the sensitivity of breast and lung cancer cells to various anticancer agents such as cisplatin, etoposide and tamoxifen." (PMID 36291810, 2022). "DNA hypermethylation of the CLDN1 promoter represses lung cancer stem cell-like phenotype and enhances chemotherapeutic efficacy." (PMID 35860691, 2022). "In lung cancer, CLDN1 expression was reported to promote the chemotherapeutic resistance of NSCLC through ULK1 phosphorylation, but methylation of the CLDN1 gene can enhance the efficacy of chemotherapy to inhibit the progress of LUAD." (PMID 36193204, 2022). "In lung cancer, claudin-1 is a key factor responsible for resistance to cisplatin, which is accomplished by activating autophagy via the upregulation of Unc-51-like autophagy activating kinase 1 (ULK1) phosphorylation." (PMID 34354941, 2021). "EMT marker analysis revealed that ZEB1 expression was increased, and Claudin-1 expression was decreased in CD44-overexpressing lung cancer cells." (PMID 34439211, 2021). "ZEB1 has been reported to promote the metastatic ability of different cancers, including lung cancer, while Claudin-1 is a metastasis suppressor in lung cancer." (PMID 34439211, 2021). "For example, in lung cancer cells, claudin-1 is upregulated through activation of the PI3K/Akt/NF-κB pathway, decreasing permeability and resulting in inhibition of the penetration of anticancer drugs into the inner area of spheroids." (PMID 34354941, 2021). "Tested lung cancer cell lines expressed not only Cldn1, but also Cldn3, Cldn4, and Cldn7 (PC‐9 cells) or Cldn3 (SK‐Mes‐1 cells)." (PMID 31825142, 2020). "Consistent with the in vitro result, these results indicated that CLDN1 sensitizes lung-cancer cells to cisplatin in vivo." (PMID 32754286, 2020). "Another study found that enhanced cell migration by tumor necrosis factor and a similar morphology like fibroblast was found to be reduced by small CLDN-1 interfering RNA in the cells of lung cancer." (PMID 31952355, 2020). "One study suggested that TNFα-induced cell migration is through cytoplasmic CLDN1 in lung carcinoma cells." (PMID 32754286, 2020). "Knockdown of PD-L1 suppressed the expression of N-cadherin, Vimentin, MMP-9 and Claudin-1 but upregulated E-cadherin expression in lung cancer cells." (PMID 32632098, 2020).
lung carcinoma (continued). "The sixth one is hsa-mir-375, which affects YAP1 molecule in lung cancer and is involved in the regulation of multiple lung cancer stages as a target of Claudin-1 in NSCLC." (PMID 32428028, 2020). "LC-MS/MS analysis in CD9 immunoprecipitates of crosslinker DTME-treated lung cancer cells identified direct interactions with claudin-1 although other claudins (claudin-2, −3, −4, −5, and −7) associated to a much lesser extent." (PMID 32091301, 2020). "The results of this study demonstrated an association between CLDN-1 and Ras/EFGR in the development of lung cancer and the combination of both has strong clinical significance." (PMID 31952355, 2020). "In vitro studies showed that basal half-life of Occludin was about ∼6 hours in primary human brain microvascular cells and basal half-life of Claudin-1 was also about ∼6 hours in human lung carcinoma cell line A549 cells." (PMID 24845399, 2014). "Conversely, the tumor suppressive activity of claudin-1 was reported in gastric cancer and lung cancer." (PMID 24009024, 2013). "Knockdown of claudin-1 in gastric cancer cells increases in vivo tumorigenicity, and claudin-1 overexpression suppresses metastasis as well as cell migration and invasion of lung cancer cells." (PMID 24009024, 2013). "In conclusion, these observations indicate that Claudin 1 acts as a critical signal mediator in TNFα-induced gene expression and cell migration in human lung cancer cells." (PMID 22675434, 2012). "Further studies indicated that Claudin 1 plays a crucial role in TNFα-induced gene expression and cell migration in human lung carcinoma cells." (PMID 22675434, 2012). "In summary, we found that TNFα stimulation induces the gene expression of Claudin 1 in human lung cancer cells, and the latter acts as the signal mediator to regulate gene expression and cell migration." (PMID 22675434, 2012). "Similarly, primary EGFR‐mutated lung cancer cells (MGH119) showed higher CEACAM5 and epithelial marker CLDN1 expression but lower mesenchymal marker CDH2 expression than their EGFR‐TKI gefitinib‐resistant counterparts (MGH119GR)." (PMID 40856433, 2025). "It shows that lung disease can affect the intestine; lung cancer can reduce the protein expression of ZO-1, Occludin and Claudin-1 in the colon tissue of mice, and ZSP can inhibit this protein expression change in the colon tissue caused by the pathological transformation of the lung and intestine." (PMID 36992837, 2023). "In A549 lung cancer cells, reduced CLDN1 expression also decreased cisplatin resistance." (PMID 36291810, 2022). "For example, CLDN1 knockdown promoted tumor growth and metastases in pancreatic cancer and lung cancer both in vitro and in vivo, indicating CLDN1 could act as a suppressor." (PMID 34116704, 2021). "Meanwhile, the level of RUNX3 was positively correlated with that of CLDN1 in lung cancer cells also implied that RUNX3 might involve in the regulation of CLDN1 expression." (PMID 32754286, 2020). "CLDN1 expression was also checked using lung cancer cell lines." (PMID 32824620, 2020). "Several studies have shown that CLDN-1 has a significant role in the pathogenesis of lung cancer." (PMID 31952355, 2020). "Based on analysis of the transcription factor binding site and searching of reference 23, RUNX3 was hypothesized to activate the expression of CLDN1 in lung cancer." (PMID 32754286, 2020). "In lung cancer, CLDN-1 acts as a cancer invasion/metastasis suppressor." (PMID 31952355, 2020). "In addition, cycloheximide treatment of human lung cancer cells revealed that RBFOX3 increases the stability of Claudin-1 through attenuation of its ubiquitination." (PMID 28126724, 2017). "In the present study, TNFα strongly increased Claudin 1 expression in human lung cancer cells." (PMID 22675434, 2012).